KRAS (KRas proto-oncogene, GTPase)
Diseases named in the same sentence as KRAS in open-access papers (continued):
Sharing a sentence is not in itself a finding about the gene and the disease.
tumor (continued). "This suggests that PSCs with elevated levels of mutant KRAS protein promote collagen deposition within the tumor microenvironment." (PMID 39810420, 2025). "To further confirm our findings, we conducted an experiment to evaluate the efficacy of the combination on resistant models which showed tumor rebound following treatment with the KRAS G12C inhibitor." (PMID 40304209, 2025). "Especially, ARID1A gene knockout, combined with overexpressing the KRAS oncogenic mutant allele (or overexpressing AKT) and c-Myc overexpression led to efficient tumor formation." (PMID 40076621, 2025). "The DEG and GSEA results suggest that tumor metabolism and the KRAS signaling pathway are different between PRNRP and KRAS-mutant PRCC." (PMID 41375035, 2025). "Mutant oncogenes and tumor suppressors directly affect tumor metabolism, with studies illustrating the connection between oncogenic KRAS genotypes and CRC metabolism." (PMID 40060193, 2025). "Silencing UCP2 in KRAS mutant cells decreases glutaminolysis, cell proliferation, and tumor growth in PDAC." (PMID 39806421, 2025). "Mutations in canonical oncogenes such as BRAF, KRAS, PIK3CA, and ALK function as dominant molecular drivers, defining biologically distinct tumor subsets characterized by specific therapeutic liabilities." (PMID 41228293, 2025). "Lactate produced by KRAS-mutant tumor cells enters CD8+ T cells through MCT1 and regulated circATXN7 expression through histone lactylation." (PMID 40611261, 2025). "Our findings extend this concept, demonstrating that platelet-mediated transfer of oncogenic KRAS can confer growth advantage to recipient tumor cells." (PMID 40244100, 2025). "KRAS G12D mutant also affect immune landscape in NSCLC by repressing CD8+ tumor-infiltrating lymphocytes (TILs) through inhibition of chemokines CXCL10/CXCL11 in NSCLC." (PMID 39806421, 2025). "Clinical observations have revealed that PD-L1 gene alterations in the context of KRAS mutations lead to in an inflammatory TME and tumor immunogenicity." (PMID 41184283, 2025). "Challenges that persist in the multi‐KRAS era include drug resistance, toxicity, and unclear interactions with the tumor microenvironment." (PMID 40485603, 2025). "KRAS mutations contribute to tumor progression and matrix remodeling in PDAC through interactions between tumor cells and their microenvironment." (PMID 39810420, 2025). "Among RAS isoforms, KRAS is particularly well known for its central role in reprogramming cancer metabolism to support tumor growth and survival." (PMID 40362656, 2025). "RMC-6236 exhibited robust anticancer efficacy across RAS-addicted cell lines and multiple tumor types in KRAS G12X xenograft models." (PMID 40361439, 2025). "Availability of small molecule inhibitors of CDK4/6 enables a combination strategy that co-targets CDK4/6 and KRAS-G12C, and its potential was preclinically demonstrated in flank tumor models." (PMID 40317086, 2025). "Although some in vivo studies have demonstrated partial inhibition of tumor progression with cetuximab, further research is necessary to fully elucidate its clinical benefit, especially in the context of KRAS-mutant tumors." (PMID 40862711, 2025).
tumor (continued). "It is supposed that the KRAS amplification mutation replaced DCTN1–ALK fusion to emerge as the driver gene, precipitating rapid and widespread tumor progression." (PMID 41246301, 2025). "KRAS G12D tumor growth was significantly inhibited by trametinib and by the ACSS2 inhibitor, although the combination of the two did not add any benefit." (PMID 40131933, 2025). "Taken together, these results demonstrate that in vivo CRISPR-based KRAS editing significantly suppresses tumor growth in NSCLC-derived PDX models." (PMID 40890128, 2025). "This section explores the primary strategies for TCR-T cell therapy, including targeting tumor antigens, viral antigens, the KRAS gene, and immune checkpoints." (PMID 40356763, 2025). "The oncogenic signaling pathway mutations consisted of KRAS, EGFR, and ALK/ROS1/RET mutations, which play crucial roles in cell proliferation and are associated with tumor aggressiveness and a higher risk of recurrence." (PMID 40507370, 2025). "Tumor cells with mutant KRAS proteins also regulate stromal cells through paracrine secretion, which affects their biological function." (PMID 39810420, 2025). "BRAF p.Val600Glu mutations were found in three left‐sided and 1 right‐sided tumour, NRAS p.Gln61Lys in 1 right and 1 left‐sided tumour, KRAS p.Lys147Glu and p.Ala146Thr in one left‐sided tumour, and HRAS p.Ala121Thr in the tumour of the rectum." (PMID 40302146, 2025). "The patients with high KRAS protein levels in their tumor had significantly longer OS than the patients with low protein levels." (PMID 40596921, 2025). "This inhibitor suppresses signaling pathways by preventing KRAS G12D/GTP/RAF1 complex formation and has been shown to cause tumor regression in preclinical models." (PMID 40731832, 2025). "Several other studies have suggested that the reaction of nitric oxide with C118 of WT KRAS promotes KRAS activation and exerts an oncogenic effect on KRAS-mediated tumor growth and proliferation." (PMID 41294676, 2025). "Consistent with our prior observations, two of the six tumor cases exhibited concurrent MAPK pathway alterations: one carried a CCDC186::RET fusion, while the other had a KRAS p.G12V point mutation." (PMID 41573641, 2025). "Inhibition of SLC7A11 resulted in cessation of GSH synthesis and targeted cell death in KRAS-mutant cancer cells, leading to the prevention of tumor development in in vivo models." (PMID 40403492, 2025). "Performance was low to moderate for tumor mutational burden (AUROC=0.67), APOBEC mutational signature (AUROC=0.57), and KRAS hotspot mutations (p.G12C: AUROC=0.74, p.G12V: AUROC=0.55, p.G12D: AUROC=0.43)." (PMID 40894597, 2025). "TCR-T cells constructed with these TCRs showed cytokine secretion and cytotoxicity against KRAS-G12V-expressing tumor cells." (PMID 39744228, 2025). "Overall, the tumor-specific allelic ratio and dosage of mutant KRAS influence PDAC biology and disease progression." (PMID 40227826, 2025). "One of the key peptides targeted in PC is mutant KRAS, as activating KRAS mutations are detected in over 90% of PDAC cases and implicated in tumor initiation and progression." (PMID 40361411, 2025).
tumor (continued). "ND646, another ACC inhibitor, induced a reduction of both tumor fatty acid production and tumor development of A549 xenograft and KRAS‐driven lung carcinomas." (PMID 40956032, 2025). "The activation of diverse signaling pathways by oncogenic KRAS facilitates tumor cell proliferation." (PMID 40090587, 2025). "Models expressing a doxycycline-induced Kras (iKras) allow for more synchronous tumor growth, which enables the study of KRAS-dependent metabolic and immune changes." (PMID 40829173, 2025). "Dual inactivation of STK11 and KRAS genes alters the tumor secretome, resulting in increased secretion of IL-6." (PMID 41051525, 2025). "It is crucial to investigate how oncogenic KRAS functionally influences the proteomic and genomic landscape, particularly its role in remodeling the tumor microenvironment (TME) and driving cancer progression." (PMID 41294676, 2025). "One of the key downstream substrates of ERK is the transcription factor MYC, which regulates tumor metabolism and is critical for KRAS-mutant PDAC growth." (PMID 40829181, 2025). "Oncogenic KRAS signaling via the ERK–MAPK–AP-1 pathway induces the expression of immunosuppressive cytokines such as TGF-β1 and IL-10, as shown in KRAS-mutant tumor models." (PMID 40524071, 2025). "These mutations commonly result in the presence of a constitutive active KRAS mutant protein, thus leading to uncontrolled cell growth, tumour formation and resistance to specific cancer treatments." (PMID 39820726, 2025). "ASOs targeting KRAS have shown promise in several studies, demonstrating efficacy in suppressing tumor growth 19-21." (PMID 40585984, 2025). "The enhanced expression of KRAS was found in tumor tissues from human subjects with HCC compared to cancer‐adjacent normal tissues, showing that the KRAS and its downstream pathways are also highly activated in HCC." (PMID 40390765, 2025). "Conversely, KRAS mutant tumours were shown to have more stable genomes, implying that they do not require as many copy number changes to progress." (PMID 41509216, 2025). "Although this line is a relevant model for evaluating the effects of sotorasib, future studies involving additional KRAS G12C mutant cell lines and tumor models are necessary to confirm the reproducibility and broader applicability of these findings." (PMID 40806294, 2025). "Subsequently, classical oncogenes such as PTEN and KRAS were demonstrated to regulate lactate metabolism in tumor cells." (PMID 39979245, 2025). "We show that aging reduces tumor initiation and growth driven by oncogenic KRAS, one of the most common oncogenic drivers across all human cancers." (PMID 41188600, 2025).
tumor (continued). "Limiting BCAA intake not only suppresses tumor growth in KRAS-mutant CRC but also enhances the efficacy of the KRAS G12D inhibitor MRTX1133 and the monoclonal antibody bevacizumab." (PMID 40437561, 2025). "Preclinical studies demonstrated its exceptional potency and specificity (IC50 < 2 nM, ~700–1000-fold selectivity over KRAS WT) and induced significant tumor regression in xenograft and immunocompetent mouse models." (PMID 41516002, 2025). "Tumor-suppressive miRNAs can serve as a therapeutic strategy to downregulate KRAS and inhibit tumor progression." (PMID 40805153, 2025). "In this review, we delve into recent advancements to understand KRAS mutant in metabolic reprogramming, emphasizing the critical role of KRAS-driven metabolism in tumor microenvironment." (PMID 39806421, 2025). "We also observed AllChAT at the locus of the MethSig cancer gene TMTC1 after co-amplification with the KRAS oncogene in both tumor PDCs, along with concomitant changes in promoter methylation." (PMID 40931149, 2025). "Genetically engineered CRC mouse models have elucidated the role of KRAS in CRC pathogenesis, showing that conditional expression of mutant KRAS alleles promotes tumor progression." (PMID 40707783, 2025). "AI-HOPE-RTK-RAS also supported the exploration of sex, tumor location, and survival outcomes in KRAS- and NF1-mutant contexts." (PMID 40868090, 2025). "Patients with hyperglycolytic CRC subtypes (CMS3), KRAS or PIK3CA mutations, or tumours featuring M2 macrophage infiltration would likely benefit most from such strategies." (PMID 41399129, 2025). "KRAS also has multiple immunomodulatory roles, not only altering the behaviors of cancer cells, but also exerting effects on a diversity of cells in tumor microenvironment (TME), like immune cells, fibroblasts and endothelial cells." (PMID 40885393, 2025). "Increased LD abundance is related to tumour aggressiveness, and reduced LD abundance can reduce the invasive ability of KRAS-mutant PDAC." (PMID 39090116, 2024). "NOP56 and mTOR cooperate to maintain homeostasis in response to oxidative stress and significantly enhance cell death in KRAS mutant tumor cells." (PMID 39712244, 2024). "Considering the lower toxicity of D-VC and its more superior effect on KRAS mutant tumor growth compared to its natural form, L-VC, it is necessary to perform clinical studies of D-VC and determine its clinical relevance." (PMID 38473779, 2024). "G12C KRAS mutant lung cancers have been reported to be likely to have a cavitary primary tumour with a higher frequency of lung metastases." (PMID 38439805, 2024). "Using KRAS-mutant LUAD tumor mouse models we have identified that trametinib-mediated Id1 downregulation sensitizes KRAS-mutant LUAD tumors to anti-PD-1/PD-L1 blockade." (PMID 38643157, 2024). "Despite there being a general increase in gene expression among the tumour xenografts compared to cells, only a single hallmark gene set was detected with higher expression in tumours versus cells (KRAS Signalling Down in PDX tumours)." (PMID 38426642, 2024). "In xenograft models, RMC-6291 outperformed adagrasib in reducing tumor volume, which paved the way for clinical trials in patients with KRAS G12C-driven tumors." (PMID 38668053, 2024).
tumor (continued). "We demonstrate that eCNTFR-Fc has widespread effects on both tumor cells and the tumor microenvironment and can sensitize cancer cells to KRAS inhibitors or immune checkpoint blockade." (PMID 38562778, 2024). "The emergence of cetuximab resistance is an inevitable outcome of cetuximab treatment of KRAS‐wild type tumours in metastatic CRC patients." (PMID 38887984, 2024). "The activation of carcinogenic KRAS signal leads the tumorigenesis and tumor progression by the variation of TME." (PMID 39882247, 2024). "AGE-mediated polarization of M2-type macrophages is observed in pancreatic cancer through excretion of KRAS-G12D by tumor cells during ferroptosis." (PMID 38853203, 2024). "Especially for those patients with KRAS-mutant tumours who have very limited targeted options available." (PMID 39516561, 2024). "Altogether, 83 FFPE tumor tissues from CRC patients listed in the NCI database were analyzed for microsatellite instability status, presence of BRAF and KRAS/NRAS mutations, and neoplastic cell percentage in tissue samples." (PMID 38539463, 2024). "There are frequent genomic alterations in these neoplasms, especially in the mitogen-activated protein kinase pathway, including BRAF (notably BRAF V600E), MAP2K1, KRAS, and NRAS mutations, and ALK gene translocation." (PMID 38713245, 2024). "A 2017 study found that KRAS mutations were detectable in 30% of patients with resectable PDAC, and the rate of detection was proportional to tumor size." (PMID 38398185, 2024). "It is well known that PDAC tumor cells are addicted to the KRAS oncogene, making the MAPK pathway anattractive target." (PMID 38727236, 2024). "In this study, we developed a novel molecular tool called tumor-targeting KRAS degrader (TKD) that effectively targets a wide range of KRAS mutants." (PMID 38937452, 2024). "KRAS modulates the activation of PI3K-AKT-mTOR pathway, therefore, the concomitant mutation between KRAS and LKB1 determine ad advantage for the tumor growth." (PMID 39763604, 2024). "Overall, the limma analysis consistently ranked KRAS as one of the top one or two genes across almost all tumor types with sufficient samples." (PMID 39455841, 2024). "Here we show that the elevated expression of DHX15 is pertinent to KRAS p.G12D mutation and DHX15 as a specific receptor in the nuclei of tumor cells interact with F. nucleatum to mediated-colorectal tumorigenesis." (PMID 38402201, 2024).